PKD1L1-AS1 (PKD1L1 antisense RNA 1)
Synonyms: C7orf69; FLJ21075
Gene: Long non-coding RNA gene on chromosome 7 (47,795,291 to 47,819,847, forward strand). Ensembl gene ENSG00000136275.
Subcellular location: Secreted
Diseases named in the same sentence as PKD1L1-AS1 in open-access papers:
PKD1L1-AS1 is named in the same sentence as 1 disease in open-access papers, as found by Europe PMC text mining. Sharing a sentence is not in itself a finding about the gene and the disease.
PKD1L1-AS1 shares sentences with these, for which no sentence is quoted: chordoma (1 paper).